VAMP3 (vesicle associated membrane protein 3)
Description:
SNARE involved in vesicular transport from the late endosomes to the trans-Golgi network.
Synonyms: CEB
Tractability: Antibody: its Gene Ontology location is reachable by antibodies, with high confidence; UniProt predicts a signal peptide or a membrane-spanning region. PROTAC: UniProt records ubiquitination sites on it; ubiquitination databases record sites on it; its protein half-life has been measured.
Gene: Protein-coding gene on chromosome 1 (7,771,296 to 7,781,432, forward strand). Ensembl gene ENSG00000049245.
Subcellular location: Early endosome membrane; Recycling endosome membrane; Synapse, synaptosome
Pathways (Reactome):
Signal Transduction: CDC42 GTPase cycle; RAC1 GTPase cycle; RAC2 GTPase cycle; RAC3 GTPase cycle; RHOA GTPase cycle; RHOB GTPase cycle; RHOC GTPase cycle; RHOD GTPase cycle; RHOF GTPase cycle; RHOG GTPase cycle; RHOH GTPase cycle; RHOJ GTPase cycle; RHOQ GTPase cycle
Vesicle-mediated transport: Cargo recognition for clathrin-mediated endocytosis; Clathrin-mediated endocytosis; Retrograde transport at the Trans-Golgi-Network
Immune System: ER-Phagosome pathway
Gene Ontology:
Molecular function: protein binding; SNAP receptor activity; syntaxin-1 binding
Biological process: mucus secretion; negative regulation of secretion by cell; positive regulation of immunoglobulin production; regulation of histamine secretion by mast cell; retrograde transport, endosome to Golgi; exocytosis; membrane fusion; positive regulation of receptor recycling; protein-containing complex assembly; SNARE complex assembly; substrate adhesion-dependent cell spreading; vesicle fusion; vesicle-mediated transport
Cellular component: clathrin-coated vesicle; cytosol; early endosome membrane; recycling endosome; recycling endosome membrane; SNARE complex; clathrin-coated endocytic vesicle membrane; membrane; phagocytic vesicle membrane; plasma membrane; trans-Golgi network membrane; transport vesicle; synapse
Genetic constraint (gnomAD): Loss-of-function variants: 11 observed, 18.69 expected, observed/expected ratio (o/e) 0.59, 90% interval 0.37 to 0.97. The upper end of that interval is the gene's LOEUF score, 0.97, which puts it in group 4 of 6, group 1 being the genes least tolerant of losing a copy. Missense variants: 122 observed, 133.42 expected, observed/expected ratio (o/e) 0.91, 90% interval 0.79 to 1.06. Synonymous variants: 49 observed, 45.49 expected, observed/expected ratio (o/e) 1.08, 90% interval 0.86 to 1.37.
Homologues: Orthologues: chimpanzee VAMP3 (100% identical), guinea pig VAMP3 (93% identical), mouse Vamp3 (90% identical), rat Vamp3 (90% identical), dog VAMP3 (88% identical), rabbit VAMP3 (87% identical), macaque VAMP3 (84% identical), zebrafish vamp3 (78% identical), tropical clawed frog vamp3 (77% identical), Drosophila melanogaster Syb (54% identical), Caenorhabditis elegans snb-2 (41% identical), Caenorhabditis elegans snb-5 (26% identical), and 2 more. Paralogues in human: VAMP2 (73% identical), VAMP1 (67% identical), VAMP5 (34% identical), VAMP7 (32% identical), VAMP8 (32% identical), VAMP4 (29% identical), SEC22B (21% identical), YKT6 (21% identical), SEC22A (12% identical), SEC22C (11% identical).
Diseases named in the same sentence as VAMP3 in open-access papers:
VAMP3 is named in the same sentence as 42 diseases in open-access papers, as found by Europe PMC text mining. Sharing a sentence is not in itself a finding about the gene and the disease. The quoted sentences say what the papers report.
periodontitis (8 papers, 2015 to 2024). An acute or chronic inflammatory process that affects the tissues that surround and support the teeth. "A conserved non-coding element within CAMTA1 upstream of VAMP3, also first identified as a genetic susceptibility locus for coronary artery disease, was found to be associated with periodontitis." (PMID 32489774, 2020). "Interestingly, gene variants in CAMTA1/VAMP3 have been suspected to be responsible for shared predisposition to both periodontitis and cardiovascular disease, which is relevant considering the nature of the present sample (MetS)." (PMID 38068972, 2023). "Interestingly, several genes among the most significant differentially methylated genes that were part of the vesicle trafficking gene sets are known to interact with the genes VAMP3 and VAMP8, which are both suggestive risk genes of periodontitis." (PMID 34732256, 2021). "There are indications that aberrant inflammatory reactivity, determined by genetic variants in the loci CDKN2B-AS1 (ANRIL), PLG, CAMTA1/VAMP3 and VAMP8 could partially explain the epidemiological link between periodontitis and cardiovascular diseases." (PMID 32489774, 2020). "Currently, more genetic loci, in addition to ANRIL, shared between ACVD and periodontitis have been identified: PLASMINOGEN and a conserved noncoding element within CAMTA1 upstream of VAMP3." (PMID 26348353, 2015).
pancreatic cancer (7 papers, 2019 to 2024). "The validated VAMP3 is generally regarded as a kind of biomarker of cell aging associated with multiple kinds of tumors, such as pancreatic cancer and breast cancer, and can reduce cell invasiveness." (PMID 35572821, 2022). "In liver cancer and pancreatic cancer, the complex of VAMP3 plays a crucial role in mediating the membrane fusion process prior to exosome secretion." (PMID 38802855, 2024). "Indeed, silencing of VAMP3 impaired cell migration and integrin-mediated adhesion in pancreatic cancer cells." (PMID 33371395, 2020). "Similarly, in pancreatic cancer cells, long non-coding RNA (lncRNA) PVT-1 and HOTAIR regulates YKT6 and VAMP3 and SNAP23 with VAMP3 colocalization, respectively, thereby playing a role in the fusion of MVBs with the plasma membrane." (PMID 38203656, 2023).
melanoma (4 papers, 2016 to 2024). A malignant, usually aggressive tumor composed of atypical, neoplastic melanocytes. "For instance, vesicle-associated membrane protein 3 (VAMP3) can be found in the MVs generated from melanoma cells, while transferrin receptors are highly enriched in exosomes, but missing in the MVs25." (PMID 27731391, 2016). "We were able to capture markedly different frequencies of VAMP3-mediated exocytosis between oligodendrocytes and melanoma cells." (PMID 38690758, 2024). "After making these adjustments, we achieved an error rate of less than 5% and found that the exocytic frequency of VAMP3 vesicles is far greater in human melanoma cells compared with primary rat oligodendrocytes." (PMID 38690758, 2024). "VAMP3 knockdown also decreased invasiveness in vitro by affecting vesicle cargo and delivery in melanoma cells." (PMID 33371395, 2020).
atherosclerosis (3 papers, 2020 to 2021). A disease characterized by the build-up of fatty material and calcium deposition in the arterial wall resulting in partial or complete occlusion of the arterial lumen. "In our further study, the role of circ_0002984/miR‐326‐3p/VAMP3 in atherosclerosis should be proved in vivo." (PMID 34169652, 2021). "In our study, we implied that circ_0002984 was increased in atherosclerosis, which resulted in the down‐regulation of miR‐326‐3p in VSMCs, consequently leading to the enhancement of VAMP3 and the progression of AS." (PMID 34169652, 2021). "In conclusion, circ_0002984 mediated cell proliferation, migration and inflammation through modulating miR‐326‐3p and VAMP3 in VSMCs, which suggested that circ_0002984 might hold great promise as a therapeutic strategy for atherosclerosis." (PMID 34169652, 2021). "We hypothesize that circ_0002984 regulates VAMP3 expression mainly through miR‐326‐3p to promote atherosclerosis progression." (PMID 34169652, 2021). "Furthermore, to explore the relationship between miR‐326‐3p and VAMP3 in atherosclerosis, VSMCs were exposed to 100 μg/mL ox‐LDL, ox‐LDL +miR‐326‐3p inhibitors or ox‐LDL +miR‐326‐3p inhibitors +VAMP3 siRNA." (PMID 34169652, 2021). "We validated the function of circ_0002984 on atherosclerosis via regulating miR‐326‐3p and VAMP3." (PMID 34169652, 2021). "During atherosclerosis, the significance of ox‐LDL/circ_0002984/miR‐326‐3p/VAMP3 signalling in the development of atherosclerosis was established." (PMID 34169652, 2021). "Notably the in vivo intervention of VAMP3/SNAP23 by systemic delivery of rapamycin ameliorates thrombi formation, echoing the value of mTOR inhibition in preventing the development of atherosclerosis." (PMID 33224946, 2020).
breast carcinoma (2 papers, 2022 to 2024). "Analysis results from Kaplan–Meier Plotter indicate that the expression of both VAMP3 and ROCK2 predicts worse OS in breast cancer patients." (PMID 38627816, 2024).
chronic myeloid leukaemia (2 papers, 2015 to 2023). "As an example, exosomes from chronic myeloid leukaemia cells were shown to require v-SNARE protein VAMP3/cellubrevin for the fusion of endosomes with autophagosomes, while VAMP7/TI-VAMP was required for fusion between the amphisome and lysosome." (PMID 28936243, 2015). "In addition, other studies found that VAMP‐7, but not VAMP‐3, is essential for exosome secretion in K562 human chronic myeloid leukemia cells, which aligns with our identification of VAMP‐7 as the R‐SNARE that mediates exosome secretion in tumour cells." (PMID 37700095, 2023).
diabetes (2 papers, 2016 to 2020). "Collectively, these data demonstrate that H2S plays an important role in modulating VAMP3 ubiquitylation to regulate free fatty acid transporters in the context of diabetes." (PMID 32257542, 2020).
gastric cancer (2 papers, 2024 to 2025). A primary or metastatic malignant neoplasm involving the stomach. "VAMP3 and NOS3 were investigated independently, and knockdown or overexpression of VAMP3 did not affect NOS3 expression in gastric cancer cells or in exosomes." (PMID 38802855, 2024).
neuroblastoma (2 papers, 2023 to 2024). Neuroblastoma (NB) is the most common solid, extracranial childhood tumor. "As a target gene of miR-124, reduced VAMP3 expression stimulates neuroblastoma cell proliferation and suppresses apoptosis." (PMID 38802855, 2024).
alveolar rhabdomyosarcoma (1 paper, 2021). A rapidly growing malignant mesenchymal neoplasm. "From the analysis of RNA-sequencing data produced in our laboratory (GEO: GSE117609), we detected both the circular and linear VAMP3 isoforms in human primary myoblasts, embryonal rhabdomyosarcoma (ERMS) RD cells and alveolar rhabdomyosarcoma (ARMS) RH4 cells." (PMID 34203273, 2021).
Alzheimer disease (1 paper, 2021). A progressive, neurodegenerative disease characterized by loss of function and death of nerve cells in several areas of the brain leading to loss of cognitive function such as memory and language. "Many of the SNARE complex genes involved in presynaptic vesicle exocytosis were significantly downregulated in Alzheimer’s disease, including SNAP-25, STX1A, SYT1 and VAMP2, while STX2, SYN1 and VAMP3 were not changed." (PMID 34423299, 2021).
chlamydial infection (1 paper, 2021). "We were unsuccessful in creating a C. trachomatis serovar L2 strain that could express IncB-FLAG, so we were unable to test this VAMP3-Inc interaction in the context of a chlamydial infection." (PMID 33229367, 2021).
chronic gastritis (1 paper, 2025). Inflammation of the stomach that is chronic in nature. "The expression levels of METTL14 and VAMP3 in Hp+ chronic gastritis tissues were much lower than those in Hp− chronic gastritis tissues." (PMID 39827141, 2025). "Moreover, the expression of METTL14 and VAMP3 in Hp+ chronic gastritis tissues is much lower than that in Hp− chronic gastritis tissues." (PMID 39827141, 2025). "To clarify the correlation between the METTL14/VAMP3 axis and H. pylori-mediated malignant transformation of the gastric mucosa, we first identified the expression of METTL14 and VAMP3 in human Hp− chronic gastritis tissues and Hp+ chronic gastritis tissues." (PMID 39827141, 2025).
chronic lung disease (1 paper, 2021). According to the definitions of the American and British Thoracic Societies, including pulmonary functional tests, X-rays, and CT scans for items such as fibrosis, bronchiectasis, bullae, emphysema, nodular or lymphomatous abnormalities. "Some of these genes, such as VAMP3, LGR5, PER3, and SDC1, were found to be involved in the different physiological functions of lung and chronic lung disease." (PMID 33407823, 2021).
Cognitive impairment (1 paper, 2021). Abnormal cognition is characterized by deficits in thinking, reasoning, or remembering. "Inhibition of Vamp3 reduces activation of microglia, potentially preventing cognitive impairments after surgery." (PMID 35155612, 2021).
Crohn disease (1 paper, 2011). A gastrointestinal disorder characterized by chronic inflammation involving all layers of the intestinal wall, noncaseating granulomas affecting the intestinal wall and regional lymph nodes, and transmural fibrosis. "A SNP near VAMP3, which encodes a V-SNARE, is also a risk factor for Crohn’s disease." (PMID 21994779, 2011). "The autophagy pathway requires many of the same proteins utilized by other membrane trafficking events, and understanding how LRRK2 and VAMP3 regulate autophagy or mucosal immunity appears important regardless of their significance in Crohn’s disease." (PMID 21994779, 2011).
gastritis (1 paper, 2025). Inflammation of the stomach. "Then, we established a gastritis mouse model of H. pylori infection to detect the expression of METTL14 and VAMP3." (PMID 39827141, 2025).
HCMV infection (1 paper, 2020). "On this basis, the role of VAMP3 during HCMV infection was explored further." (PMID 32910773, 2020).
Lewis lung carcinoma (1 paper, 2023). "To verify no homologous circVamp3 in mice, we designed the divergent and convergent primers to amplify the circVamp3, circIpo11(positive control, which was verified to exist in mice), and Vamp3 mRNA in Lewis lung carcinoma (LLC1) cell lines of C57BL mice and the lung of BLAB/c." (PMID 37603540, 2023).
liver cancer (1 paper, 2024). An epithelial or non-epithelial malignant neoplasm that arises from the liver. "In liver cancer, the complex of SNAP23 and VAMP3 promotes the secretion of exosomes in the tumor microenvironment (TME)." (PMID 38802855, 2024).
metabolic syndrome (1 paper, 2017). A cluster of metabolic risk factors for CARDIOVASCULAR DISEASES and TYPE 2 DIABETES MELLITUS. "Decreased expression of specific ANRIL isoforms is reported to affect expression of ADIPOR1 (adiponectin receptor with a role in fatty acid catabolism and inflammation), VAMP3 (membrane protein with a role in phagocytosis) and C11orf10 (in proximity to genes associated with metabolic syndrome)." (PMID 29227965, 2017).
synovial sarcoma (1 paper, 2017). "VAMP3 is known to mediate release of inflammatory cytokines by the murine macrophage cell line RAW264.7 and the human synovial sarcoma cell line SW982." (PMID 28524818, 2017). "Indeed, our data show that siRNA knockdown of VAMP3 impairs IL-6 secretion by monocyte-derived dendritic cells as previously observed for RAW264.7 murine macrophages and SW982 human synovial sarcoma cells." (PMID 28524818, 2017).
thrombosis (1 paper, 2020). "Our study has fully proved that flow disturbance accelerates the FeCl3-induced thrombosis and the effects are dependent on the VAMP3 and SNAP23-mediated VWF secretion." (PMID 33224946, 2020).
triple-negative breast carcinoma (1 paper, 2024). An invasive breast carcinoma which is negative for expression of estrogen receptor (ER), progesterone receptor (PR), and human epidermal growth factor receptor 2 (HER2). "This study investigates the involvements of a CCAAT enhancer binding protein delta (CEBPD)/vesicle associated membrane protein 3 (VAMP3) axis in paclitaxel (PTX) resistance and immune evasion in triple-negative breast cancer (TNBC)." (PMID 38627816, 2024).
viral infections (1 paper, 2023). "These KEGG pathways are often associated with cell signaling and viral infections, probably relating to VAMP3′s role in membrane fusion and vesicle transport." (PMID 37834325, 2023).
tumor (17 papers, 2014 to 2025). "The GSE62564 dataset contains both miR-124 and VAMP3 expression data from the same NB patients and tumor samples, allowing us to analyze the impact of miR-124 and VAMP3 on NB simultaneously." (PMID 37834325, 2023). "For instance, ARF6 is responsible for the packaging of vesicle associated membrane protein (VAMP3), integrin β-1, and MHC I into tumor-cell derived MVs, as well as the simultaneous exclusion of transferrin receptors." (PMID 36045692, 2022). "Other packaging mechanisms also involve the use of SNARE proteins, particularly VAMP3, which when associated with CD9 facilitates its packaging into tumor-derived MVs." (PMID 36045692, 2022). "VAMP3 functions during the degradation of extracellular matrix and subsequent cellular invasion in tumor." (PMID 32432045, 2020). "Additionally, the CEBPD/ VAMP3 axis increases extracellular PD-L1 levels via the paracrine EVs, consequently dampening the anti-tumor immune response." (PMID 38627816, 2024). "Therefore, it can be inferred that VAMP3 can increase the extracellular PD-L1 expression to suppress the T cell-mediated anti-tumor immune response." (PMID 38627816, 2024). "We propose that WDFY2 acts as a tumor suppressor by serving as a gatekeeper for VAMP3 recycling." (PMID 31253801, 2019). "By real-time qPCR, we further examined the expression of selected genes (Pkm, Ppp1r13l, Vamp3, Ctnnb1, Tbc1d4, Ppp1r21, C1qtnf9, Fgf3 and Efemp2) that are known to be involved in the tumor development or potentially relevant for establishment of malignant transformation." (PMID 29073177, 2017). "For example, VAMP3, VAMP7, and YKT6 affect exosome secretion by regulating the exocytosis of tumor cells." (PMID 38802855, 2024). "Here, the authors show that WDFY2 interacts with the v-SNARE VAMP3, leading to a suppression of the metalloprotease MT1-MMP secretion, suggesting that WDFY2 acts a tumour suppressor by suppressing MT1-MMP secretion." (PMID 31253801, 2019). "Similarly, the CD8+ T cells were sorted from the harvested xenograft tumor tissues, in which the cell exhaustion was decreased by sh-CEBPD but promoted by oe-VAMP3." (PMID 38627816, 2024). "Additionally, the CEBPD/VAMP3 axis also increases extracellular PD-L1 level, delivered by cancer cell-derived EVs, to suppress CD8+ T cell-mediated anti-tumor immune response." (PMID 38627816, 2024). "Similar to the association pattern seen in TCGA survival data, in vivo tumorigenesis by KRAS-dependent human tumor cells in immune deficient mice required SNAP23 and VAMP3, but not SNAP29." (PMID 31712554, 2019). "Moreover, cellular transport was also compromised in tumor cells through downregulation of 38 proteins related to vesicle-mediated transport, as well as important proteins involved in vesicle docking involved in exocytosis (such as VPS33B, RAB3D, VAMP3, and SCFD1)." (PMID 39202022, 2024).